IL2 (interleukin 2)
Diseases named in the same sentence as IL2 in open-access papers (continued):
Sharing a sentence is not in itself a finding about the gene and the disease.
tumor (continued). "These rewired cells ultimately activate the same critical pathways (TCR and IL-2 pathways) as seen in native T cell responses but do so in a different temporal order and in response to different inputs allowing them to be far more effective as a tumor-targeted therapy." (PMID 36520915, 2022). "Critically, in either the autocrine or paracrine configuration, the synthetic IL-2 circuit did not cause a reduction in the contralateral NY-ESO+/GFP− tumor (lacking the synNotch ligand), highlighting the precisely targeted impact of the synthetic IL-2 circuit." (PMID 36520915, 2022). "The levels of IL-2 and IFNγ cytokines released from unstimulated lymphocytes treated with tribodies were found to be very low, thus proving that the effects of the tribodies are exerted only on activated lymphocytes expressing the ICs in the presence of tumor cells." (PMID 36071464, 2022). "There are several cytokines to examine in addition to IL-2, and cytokine exposure often leads to metabolic changes, so functional mitochondrial assessment can provide illuminating data regarding the mitochondrial health and anti-tumor potential of the CAR T cell." (PMID 35645205, 2022). "We showed that DMXAA improved antigen presentation, yet CTL function was compromised, therefore we hypothesized that combining DMXAA with an agonist anti-CD40 antibody that activates DCs or with IL-2 that expands tumor-specific T cells might improve DMXAA efficacy." (PMID 36466911, 2022). "Taken together, TKD/IL-2 pre-stimulation of NK cells and their subsequent interaction with tumor cells expressing mHsp70, influences the expression of functional receptors and triggers an effective anti-tumor cytotoxic response, the potency of which is dependent on the expression of mHsp70." (PMID 35720311, 2022). "In addition, MHT treatment was found to enhance NK cell recruitment at tumor sites, positively influence IL-2-activated NK cell degranulation and release IFN-γ, and may enhance GBM susceptibility to NK cell-mediated killing." (PMID 35651605, 2022). "To assess more stringent requirements that may functionally demonstrate the exhaustive phenotype shown in the CAR T cell products, we next examined the ex vivo expansion potential and IL-2 production of patient-derived CAR T cells (n = 22) upon exposure to tumor cells." (PMID 35406703, 2022). "In addition, higher IFN-γ and IL-2 secretion was observed in tumor of treated mice." (PMID 33986437, 2021). "The effector function of CD8+ T cells could be boosted by a prodrug formulation of recombinant IL-2 (NKTR-214) that proved to increase the tumor-fighting potential of a 16 Gy single dose, even in contralateral unirradiated tumor site among mice with implanted fibrosarcoma or colorectal cancers." (PMID 34209192, 2021). "In addition, previous study showed that selenium nanoparticles could increase the levels of cellular immunomodulatory components (granzyme B, IL-12, IFN-γ, and IL-2) to boost the immune response in mice bearing tumor exposed to crude antigens of 4T1 cells." (PMID 34393797, 2021). "However, when high-dose IL-2 was administered together with TILs, objective tumor regression could be observed in 34% of patients who were refractory to single-agent IL-2 treatment." (PMID 34193217, 2021). "An NKG2D-Fc-IL2 DNA vaccine in combination with a therapeutic human papillomavirus type 16/E7 peptide vaccine was able to result in accumulation and proliferation of E7-specific T cells at the tumor site and reduced tumor growth that resulted in prolonged survival of tumor-bearing mice." (PMID 34790830, 2021). "Moreover, a recent study demonstrated that the combination of anti-Tim3 mAb, T-cell redirecting bispecific antibody MT110 (EpCAM x CD3), and IL2 could further enhance the anti-tumor effects of the transfused Vγ2Vδ2 T cells in tumor-bearing nude mice." (PMID 34040604, 2021).
tumor (continued). "Moreover, delivery of IL-2 to the TME as a result of AnnV-mediated tumor localization could support survival and effector functions of tumor infiltrating lymphocytes." (PMID 34804041, 2021). "In addition, immune modulating pathways, such as IL-2 and Dap12, were altered in AKPr which may enable circulating tumor cells to survive in circulation." (PMID 33671932, 2021). "Interestingly, tumors of mice vaccinated with Ad-mAFP-DC (6–10 days after tumor induction) already showed changes within the tumor into a shift towards a Th1 cytokine milieu, expressing significantly more IL-12, IFNγ, IL-2 and GM-CSF compared to mice vaccinated with Ad-LacZ-DC (p < 0.05)." (PMID 34282787, 2021). "Additional studies have demonstrated that low levels of CD57+ NK cells were found to be an independent immune risk factor affecting the prognosis of mRCC patients treated with IL-2, indicating that activated NK cells may be critical for IL-2 to exert its anti-tumor activity." (PMID 33746989, 2021). "Meanwhile, the selenylated sweet potato polysaccharides could scavenge free radicals much efficiently, and also could inhibit tumor growth, increase the secretion levels of IL-2 and TNF-α but decrease the serum vascular endothelial growth factor (VEGF) level in the murine H22 hepatoma mice model." (PMID 34829068, 2021). "This knowledge may also shed light on the contrasting effects of IL2-based tumor therapies." (PMID 33498681, 2021). "In addition, the CAR-T cells show IL2 secretion and specific cell lysis upon tumor cell engagement." (PMID 33567640, 2021). "IL-2 was first developed as single-agent therapy for metastatic melanoma, kidney cancer, and non-Hodgkin lymphoma, where it shows some benefit in eliciting anti-tumor immune responses (50% tumor reduction in 15–20% of patients), presumably by activating T lymphocytes." (PMID 34193217, 2021). "Programmed death ligand 1 on the cell surface facilitates tumor immune escape by inducing activated T cell apoptosis, promoting T cell weakness, enhancing the function of regulatory T (Treg) cells, inhibiting T cell proliferation, activating damaged T cells, and stimulating the production of IL-2." (PMID 34722545, 2021). "Finally, high tumor expression of transcripts encoding the activating NK cell receptors, KLRK1 and the CD160–TNFRSF14 receptor–ligand pair, was strongly correlated with the IL-2-expanded NK cell phenotype and improved BLCA prognosis." (PMID 34858395, 2021). "Additionally, tumor cells expressing IL2Rα at the membrane may compete with effector T cells for IL2, a tumor immune evasion strategy that, until now, was solely attributed to Tregs." (PMID 33498681, 2021). "Preliminary studies using ex vivo IL-2 expansion of tumor infiltrating lymphocytes (TILs) and peripheral blood immune cells followed by autologous transfer into the cancer patients demonstrated the expansion of these cells with weak antigen specificity and poor anti-tumor effect." (PMID 33918403, 2021). "Similarly, NK cells can be chemoattracted by CXCL9 and specifically recognize IL-2 on tumor cells." (PMID 34603454, 2021). "The dietary antioxidant curcumin could partially reverse the inhibition of IL-2 stimulated NK cell tumor cytotoxicity mediated by tumor exosomes, microvesicular bodies containing a distinct set of intracellular and cellular membrane components that are secreted by cancer cells to body fluids." (PMID 33572626, 2021). "Some important immune-associated genes, such as granzyme B, IFN-γ, IL-2, IL-12, FoxP3 and STING, are regulated via epigenetic mechanisms in immune or/and cancer cells, as are immune checkpoint molecules (PD-1, CTLA-4, TIM-3, LAG-3, TIGIT) expressed by immune cells and tumor-associated stromal cells." (PMID 34930302, 2021). "In addition, experimental models demonstrated that either high dose injection of IL-2 alone, adoptive transfer of ex vivo cultured lymphocytes, or concurrent IL-2 and lymphocyte administration could deliver potent anti-tumor activity." (PMID 34140957, 2021).
tumor (continued). "Indeed, several experiments confirmed the presence of an anti-tumor immunity provoked by hyperthermia and an increased anti-tumor action of combined treatment employing hyperthermia and immunotherapy with cytokines such as interleukin-2 (IL-2) and GM-CSF." (PMID 34835555, 2021). "High-dose IL-2 oftentimes induces systemic toxicity that requires intensive monitoring and care, and could also promote regulatory T cells that suppress the anti-tumor response of TIL." (PMID 34112147, 2021). "In addition, effector and memory CD8+ T cell responses could also be induced by IL-2, indicating its crucial role in the T cell–mediated anti-tumor process." (PMID 34497832, 2021). "Similarly, also tumor-infiltrating dendritic cells have been shown to take part in antigen presentation and priming of CTLs with exogenous antigens and to trigger secretion of the inflammatory cytokines interleukin 2 (IL-2) and interferon gamma (IFNɣ)." (PMID 33592498, 2021). "In details, in all the analyzed patients and independently from the tumor site of origin, the levels of IL-6 increased after 10 days of treatment with lanreotide and decreased in the following six months; whereas the levels of IL-2 and IL-10 raised only in some patients." (PMID 32766136, 2020). "Moreover, PTPN2‐deficient CAR T cells were effective in repressing tumour growth even without the co‐administration of IL‐2 that is used routinely in rodent pre‐clinical models to promote CAR T‐cell expansion but is not used in the clinic." (PMID 31803974, 2020). "Similarly, a treatment that would lead to an increase of IL-2 could kill the tumor cells faster at t = 200 h." (PMID 33281620, 2020). "The IL2 expression-mediated therapeutic effect of hADSCs may be offset by an increased expression of oncogenes, as well as the innate ability of hADSCs to support tumor growth and suppress T-cell proliferation." (PMID 32560387, 2020). "Indeed, many cytokines may elicit anti-tumor effects, including IL-2, IL-12, IL-15, IL-21, IFN-alfa and Granulocyte-Macrophage Colony-Stimulating Factor GM-CSF." (PMID 33597950, 2020). "Hence, IL-2 is deemed to be pivotal to immune homeostasis and an abundance of Tregs in the tumor could exacerbate the constraint of IL-2 limitation on Tconv cells." (PMID 33375291, 2020). "In addition, we also observed that mice that received combination treatment demonstrated significantly higher levels of IFN-γ, TNF-α, and IL-2 in tumor supernatant and blood when compared to control or single treatment groups, confirming that LB-100 increased cytokine secretion." (PMID 31935881, 2020). "Moreover, it would be valuable to determine if stimulation of NK cells with HSP70/IL-2 could induce a memory of NK cells to prevent future tumor recurrence." (PMID 32218162, 2020). "In addition, the amounts of IFN-γ and IL-2 were lower in α19BBZ-LRP6 CAR-T cells than that in α19BBZ CAR-T cells after stimulation by the tumor cells, which suggests that the α19BBZ-LRP6 T cells may have a lower risk of developing cytokine-releasing syndrome." (PMID 33042788, 2020). "Additionally, OAd.TNFa-IL2 may induce antitumor effects through trough AIM2 activated, gasdermin-induced cell killing, with associated immunogenic tumor microenvironment modulation." (PMID 32225009, 2020). "Further research showed that 1-MT effectively slows the growth of tumor cells and enhances the effect of chemotherapy drugs through significantly enhancing the sensitivity of the immune system to tumor antigens and enhancing the expression of IL-2 levels within the tumor microenvironment." (PMID 32912307, 2020). "Furthermore, EpCAM-specific antibodies were conjugated with bouganin (citatuzumab bogatox), Pseudomonas exotoxin A (oportuzumab monatox) and alpha-amanitin, with interleukin-2 to activate T cells in the vicinity of EpCAM-positive tumor cells (huKS-IL2), and with encapsulated inhibitory RNAs." (PMID 32507912, 2020).
tumor (continued). "In addition, blockade of CTLA-4 induced increased secretion of IL-2 by tumor cells, suggesting that the receptor regulates cellular functions that may impact the immune microenvironment." (PMID 32850353, 2020). "Pre-treatment with the cytokine interleukin 2 (IL-2) increases the anti-tumor response rate to oxaliplatin particularly in patients with low blood lymphocyte counts but there are currently no data available on how this immune modulation may impact on the neuropathic side effects of chemotherapy." (PMID 32153361, 2020). "Although adoptive transfer of tumor-sensitized and antigen-reactive TILs with prefatory lymphodepletion and IL-2 dosing regimens had proven effective in the clinic, patient responses were often transient: shrinkage in metastatic lesions could occur, without objective response to treatment." (PMID 32283684, 2020). "However, a significant increase in CD8+ T cells with an effector memory profile (CD62L-CD44+) was observed in the mice that received UnLicNK cells or total NK cells compared to IL-2 HCT controls, a subset which reconstitution has been associated to control of tumor growth." (PMID 33488624, 2020). "Moreover, IFN-γ and IL-2 could induce neutrophils to express granzyme B, which was directly cytotoxic to tumor cells." (PMID 32422991, 2020). "Therefore, MSC-based delivery of IL2 to tumor sites may increase the number of tumor infiltrating NK cells and increase overall survival of some patients." (PMID 32560387, 2020). "However, when we further studied the function of tumor infiltrating lymphocytes, we found that intravenous iron supplementation significantly reduced the production of cytokines IL-2 and IFNγ by tumor CD8+ cytotoxic T cells, indicating iron-dependent reduced functionality of these cells." (PMID 33344239, 2020). "By using an ex vivo ovarian cancer (OVCA) model derived from patient samples, enhanced levels of proinflammatory signals (IFNγ, CXCL10, TNFα and IL-2) associated with a concomitant activation of CD4 and CD8 TILs could be observed when tumor cells were infected with TILT-123." (PMID 33202717, 2020). "The use of mesenchymal stem cells (MSCs) may be a potential strategy that can reduce systemic toxicity and ensure targeted delivery of IL2 as well as maintain high levels of IL2 in the tumor microenvironment, since MSCs have the ability to migrate toward tumor sites in vivo." (PMID 32560387, 2020). "Lastly, to evaluate whether the epigenetic reprogramming mediated by Phf19 result in augmented antitumor function we adoptively transferred pmel-1 cells overexpressing Phf19, Phf19mut, or Thy1.1 into tumor-bearing mice in conjunction with administration of gp100-VV and IL-2." (PMID 31089138, 2019). "Therefore, we next considered whether IL2-induced metabolism is important for the effector function and survival of NK cells interacting with tumour cells." (PMID 31595191, 2019). "Several recent studies show that immunocytokine efficacy and biodistribution of IL-2 variants may not be sufficiently attributed to tumor-antigen targeting." (PMID 31462678, 2019). "The stimulation of NK cells with IL-2 generates the so called lymphokine activated killer (LAK) cells which display increased cytotoxic potential against a variety of resistant tumour cells, and therefore, may be used in adoptive therapy of some types of cancer." (PMID 31540116, 2019). "Thus, our data suggest the possibility that competition with IL-2 secreted in the tumor microenvironment could also contribute to the low specific tumor targeting of IL-2-based therapeutics." (PMID 30808414, 2019). "The tumor-bearing host (mean diameter of tumor 5–8 mm) received a lymphodepleting dose of total body irradiation, pmel-1 T cells adoptively transferred intravenously into B16 tumor-bearing mice and gp10025-33 peptide-pulsed dendritic cell vaccination with high-dose IL-2 therapy." (PMID 31067680, 2019).
tumor (continued). "Also, while it is known that NK cells can operate alongside antitumour T cells responses, how the signals received from tumour cell interactions (NK receptor ligands) and T cell derived signals (IL2) cooperate with respect to NK cell metabolic and functional responses is not known." (PMID 31595191, 2019). "In addition, we observed that co-culture of DLBCL cell lines with primed T cells in the presence of anti-LAG-3 and anti-TIM-3 induced potent dose-dependent increases in in vitro cell death via AcellaTox and IL-2 ELISA assays, suggesting potent anti-tumor activity of these compounds." (PMID 31007846, 2019). "Increases in PD-L1 expression can occur on SCC cells as a result of mutations in tumor cell signaling pathways or exposure of tumor cells to inflammatory cytokines IL-1, IL-6, GM-CSF, IFNγ, TNFα, and VEGF and the gamma-chain cytokines IL-2, IL-7, IL-10, IL-15, and IL-21." (PMID 31554151, 2019). "Similarly, the combination of Tα1 and IL-2 after Cy treatment induced complete tumor regression, thus reinforcing the notion that combining immunotherapy with chemotherapy might be an effective anti-tumor strategy." (PMID 31555601, 2019). "However, the higher affinity of IL-2 over the antibody might actually limit tumor targeting of Ab-IL2." (PMID 31462678, 2019). "Moreover, tumor growth suppression by hRT + IL-2c was significantly better than that by hRT + IL-2." (PMID 30808414, 2019). "However, IL2 has a big disadvantage in cancer as it targets Tregs, which are the cells that constitutively express the highest affinity (αβγ) receptor for this cytokine, leading to their expansion and, thus, increased tumor suppression." (PMID 31614774, 2019). "Furthermore, when activated human T cells were co-cultured with PD-L1 positive human tumor cells, PD1-Fc-OX40L was observed to concentrate to the immune synapse, which enhanced proliferation of T cells and production of IL-2, IFNγ and TNFα, and led to efficient killing of tumor cells." (PMID 30563566, 2018). "Importantly, the capacity of priming and IL-2 stimulation to trigger cytotoxicity was patient-dependent and mutually exclusive, in that NK cells from ~50% of patients preferentially responded to tumor priming, whereas NK cells from the remaining patients preferentially responded to IL-2 stimulation." (PMID 30761160, 2018). "Furthermore, young, but not elderly, IL-2/CD40-treated mice demonstrated additional reductions in other regulatory markers expressed by tumor-associated CD4+ T cells, including ICOS and IL-10." (PMID 30560130, 2018). "Taken together, our data suggested that the prolonged survival of C6 mice by oncoVV-HddSBL might be due to the significant reduction of IL-2 secretion from tumor cells, whereas the activation of inflammatory transcription factors NF-κB and AP-1 limited this effect." (PMID 29701680, 2018). "However, the frequency of IL-2 + cells within the tumor was much lower than in the control." (PMID 29844317, 2018). "Furthermore, NK cell activity against membrane HSP70–positive tumour cells which initially was found to be very low in all tumour patients could be re-stimulated by an ex vivo stimulation with HSP70 peptide plus IL-2 as a growth factor." (PMID 29203711, 2018). "e.g., vessel specific-delivery of IL2, a cytokine known to stimulate the proliferation of cytotoxic T-cells, natural killer cells, and regulatory T-cells, resulted in an additive or synergistic anti-tumor effect when the administration of this immunocytokine was combined with radiotherapy." (PMID 30250827, 2018). "We did not investigate which IL-2-associated signaling pathways may help mediate the tumor-promoting effects of IL-2Rα in NKTCL, nor did we examine the immunomodulatory effects of IL-2Rα in NKTCL." (PMID 30340635, 2018).